PTX3 (pentraxin 3)
Diseases named in the same sentence as PTX3 in open-access papers (continued):
Sharing a sentence is not in itself a finding about the gene and the disease.
cancer (continued). "The activation of PTX3 in M2 macrophages or CAFs promotes the growth, metastasis, and invasion of drug-resistance cancer." (PMID 30740360, 2019). "PTX3 is a key molecule playing complex regulatory roles at the crossroads of innate immunity, inflammation, tissue repair and cancer." (PMID 31057548, 2019). "Our results show that prostate cells, especially cancer cells, express PTX-3, an innate-immune protein." (PMID 30627063, 2018). "Evidence suggests that PTX3 is a key homeostatic component at the crossroad of innate immunity, inflammation, tissue repair, and cancer." (PMID 30687307, 2018). "Based on the observation that PTX3 expression was essential for oleate-enhanced cancer cell metastasis, we next studied the mechanisms involved in PTX3-regulated cell metastasis." (PMID 28489600, 2017). "SAP and PTX3 can affect tumors, either by regulating cancer-related inflammation, angiogenesis, or directly inhibiting cancer cell growth and differentiation." (PMID 29202702, 2017). "Pentraxin 3 (PTX3) as an inflammatory molecule has been shown to be involved in immune response, inflammation, and cancer." (PMID 27377307, 2016). "In bone metastatic gastric cancer, PTX3 knockdown using small interfering RNA significantly inhibited BDNF-induced interactions of cancer cells with osteoblasts." (PMID 27458153, 2016). "The CEBPD downstream target PTX3 that we focused on here can provide a great opportunity for developing a feasible translational application for cancer therapy." (PMID 26124179, 2015). "The in vivo result implies that PTX3 can play an autocrine/paracrine role to stimulate pro-growth factor(s) from stromal cells surrounding cancer cells." (PMID 26124179, 2015). "We further developed a PTX3 inhibitor RI37 peptide to prevent CEBPD/PTX3 axis-induced cancer malignancies and reduce the metastasis and invasion of drug-resistant cancers." (PMID 26124179, 2015). "EGF-mediated PTX3 secretion resulted in the enhancement of cell migration and invasion, and interactions between cancer and endothelial cells." (PMID 25797258, 2015). "Based on the observation that PTX3 expression is essential for EGF-enhanced cancer metastasis, we next clarified the mechanisms involved in PTX3-regulated cell metastasis." (PMID 25797258, 2015). "Finally, to study the activation of complement system in association with MUC1 expression, we evaluated the deposition of PTX3 and C3 in cancer tissue." (PMID 41533164, 2026). "The opposite roles of PTX3 within a single cancer type may also be explained by the involvement of different signaling pathways." (PMID 41479916, 2025). "It is particularly intriguing to consider whether PTX3 is regulated by epigenetic mechanisms, such as DNA methylation or histone modification, as the expression levels of PTX3 can vary within a single cancer type, sometimes exerting opposing effects." (PMID 41479916, 2025). "The role of PTX3 in cancer development and progression has been extensively investigated." (PMID 41479916, 2025). "Functional enrichment analysis revealed that DEGs associated with PTX3 are significantly enriched in several key pathways, including cytokine-cytokine receptor interactions, the PI3K-Akt signaling pathway, and transcriptional dysregulation in cancer." (PMID 40656950, 2025). "Furthermore, we critically examine the challenges and translational opportunities of PTX3, aiming to inform future research directions and therapeutic strategies for cancer management." (PMID 41479916, 2025). "This review summarizes the role of PTX3 in various cancer types." (PMID 41479916, 2025). "Collectively, these findings suggest that PTX3 may play an active role in the inflammation-to-cancer transition, warranting further experimental investigation." (PMID 41479916, 2025). "There are conflicting reports regarding the role of PTX3 protein in cancer." (PMID 39594709, 2024). "PTX3 is vital in innate immunity, inflammation, cancer, and tissue repair and remodeling." (PMID 38474359, 2024).
cancer (continued). "Notably, inhibition of PTX3 has been found to reduce these aggressive characteristics, further emphasizing its role in cancer progression." (PMID 39594709, 2024). "Studies suggest that PTX3 plays both supportive and harmful roles in cancer development." (PMID 39594709, 2024). "However, several in vitro experiments performed with manipulation of PTX3 expression indicated that PTX3 acts as a cancer promotor through inducing epithelial‐mesenchymal transition and macrophage chemotaxis." (PMID 39187920, 2024). "PTX-3 expression levels are related to the prognosis in certain cancers, including HCC." (PMID 39061656, 2024). "Additionally, PTX3 (rs73158510) is a putatively imprinted locus that showed biallelic expression in three TNBC cancer cells (patient BC11), corroborated by the bulk RNA (LOI) results for the closely related basal-like subtype." (PMID 39766305, 2024). "Long pentraxin (PTX3) has been defined as a possible link between inflammation and cancer." (PMID 38339243, 2024). "PTX-3 acts as a linker between innate immunity, inflammation, tissue repair, and cancer." (PMID 39061656, 2024). "Pentraxin 3 (PTX3), originally identified as a pattern‐recognition molecule for defence against infectious agents, has multiple functions in tissue repair and in the regulation of cancer‐associated inflammation." (PMID 39187920, 2024). "PTX3 has been reported to exert complex effects on cancer progression." (PMID 38243273, 2024). "Thus, the search for new molecular biomarkers and targets that drive the immune system is crucial for cancer research, and, in this regard, PTX3 can represent possible candidates." (PMID 38730589, 2024). "Notably, PTX3 protein levels were still too low to be detected in cancer cells under 5-azacytidine treatment, and only SW620 displayed detectable protein amounts." (PMID 38243273, 2024). "Due to the growing need to explore new biomarkers and therapeutic targets for the detection and treatment of cancerous lesions, we sought to elucidate the role of Pentraxin-3 in the progression of cancerous lesions, as it is involved in the process of angiogenesis and inflammation." (PMID 38136377, 2023). "It is possible that PTX3 may have different functions on cancer development depending on the tissue and cancer type." (PMID 37025408, 2023). "Moreover, the expressions of CD59, C3aR, and C5aR colocalized with PTX3 in MUC1H cancer tissue (respectively)." (PMID 36902242, 2023). "Interestingly, in this study, the authors showed that the concentrations of Pentraxin 3 were significantly correlated with the concentrations of NF-kB and IL-6, which confirmed the involvement of PTX3 in cancer-associated inflammation." (PMID 38136377, 2023). "Interestingly, PTX3 not only participates in the activation of the immune system, but has also been connected to cancer progression." (PMID 38136377, 2023). "In cancer, a PTX3/TLR4 interaction has been recently reported only for invasive melanoma." (PMID 37749607, 2023). "The role of PTX3 as biomarker of cancer has been investigated." (PMID 37025408, 2023). "Additionally, in steroid hormone-regulated cancers, PTX3 can bind to the FGF8b receptor and prevent the proliferation of cancer cells." (PMID 38136377, 2023). "PTX3 is acknowledged as an important player in tissue remodeling and cancer." (PMID 37885881, 2023). "However, these three signaling pathways were more closely related to GBM cells with low expression of PTX3, indicating the potential anti‐cancer ability of PTX3 in GBM." (PMID 35855654, 2022). "PTX3 in cancer can act as an oncosuppressor or a protumorigenic factor." (PMID 36555812, 2022). "In addition, Ptx3 is also an inflammatory molecule related to cancer proliferation, invasion, and metastasis." (PMID 36605216, 2022). "Consistently, PTX3 mRNA expression was low in the paired pan-cancer samples except for CHOL." (PMID 36139597, 2022).
cancer (continued). "In addition to providing defense against infectious agents, PTX3 plays several functions in tissue repair and in the regulation of cancer-related inflammation." (PMID 35681634, 2022). "PTX3 belongs to the pentraxin family, which is produced as response to inflammatory mediators and has numerous functions in different physiopathological conditions, including cancer." (PMID 36290747, 2022). "Specifically, KIRC cancer cell growth and migration could be significantly suppressed by blocking PTX3 with siRNA in vitro." (PMID 36139597, 2022). "PTX3 data profiles and clinical information in TCGA cancers were obtained from different public databases to clarify the expression levels, genetic alterations, prognostic significance, underlying mechanisms, and the predicted role in immunotherapy of PTX3 across TCGA cancers." (PMID 36139597, 2022). "Previous studies have concurred that PTX3 played an ambivalent role in different cancer types." (PMID 36139597, 2022). "However, the activation of stromal PTX3, including fibroblast PTX3, can still support cancer progression." (PMID 35090088, 2022). "We systematically conducted a pan-cancer analysis of PTX3, which might be clinically valuable for precise and personalized treatment." (PMID 36139597, 2022). "Their study reiterates the idea that PTX-3 could be used as a target in cancer types where FGF2 and angiogenesis are involved in pathogenesis (especially in hormone dependent tumors), consistent with other studies." (PMID 36499628, 2022). "The bioinformatic analysis showed that PTX3 played a crucial role in human cancers including KIRC." (PMID 36139597, 2022). "This is the first study showing an epitranscriptomic control of PTX3 that can be of great interest for a better understanding of the role/action of PTX3 in different cancers and for future therapeutic interventions crossing immunity, tissues remodeling, and cancer." (PMID 36009036, 2022). "This review elucidates the potential usefulness of PTX-3 as a serum biomarker in cancer." (PMID 36499628, 2022). "We found that PTX3 expression was negatively correlated with promoter methylation levels and PTX3 promoter methylation could influence cancer patient prognosis." (PMID 36139597, 2022). "Conclusively, our study shows a comprehensive bioinformatic analysis of PTX3, which might serve as a pan-cancer prognostic biomarker." (PMID 36139597, 2022). "This alteration might lead to the PTX3-mediated promotion of cellular proliferation, angiogenesis, and insensitivity to apoptosis, possibly leading to cancer cell invasion and migration." (PMID 34572075, 2021). "Chronic inflammation is a key factor in the development and progression of cancer, suggesting that PTX3 may play an important role in cancer." (PMID 33952272, 2021). "PTX3, a modulator of inflammatory processes, is a member of the highly conserved pentraxin superfamily, which includes CRP, and it is associated with disease severity and mortality in patients with cancer." (PMID 33776564, 2021). "Furthermore, PTX3 inhibited GCCs metastasis into milky spots by attenuating the polarization of the M2 phenotype and reducing cancer cell stemness in milky spots." (PMID 34149932, 2021). "The results showed that we could significantly distinguish malignant tumors from borderline tumors and normal ovarian epithelial tissues based on the expression level of PTX3 (AUC = 0.919, p < 0.001)." (PMID 33952272, 2021). "Several studies have indicated that PTX3 behaves as an oncosuppressor and may exhibit potential therapeutic effects in the treatment of cancer." (PMID 34048179, 2021). "Overexpression of PTX3 might prevent the cell incursion plus EMT in cancer cells in vitro as well as in vivo." (PMID 32194791, 2020). "Therefore, a clear definition of its functions in specific cancer types is of practical importance for clinical application of PTX3 in diagnosis and therapeutics." (PMID 32427938, 2020).
cancer (continued). "In addition, PTX3 is involved in the occurrence and development of cancer and can be used as a marker of cancer progression." (PMID 31957804, 2020). "Considering the key function of galectin-3, IL-6, chemerin and pentraxin-3 in inflammation and cancer, the altered secretome may be a consequence of malignant cell transformation." (PMID 33066326, 2020). "This alteration might lead to the PTX3-mediated promotion of cellular proliferation, angiogenesis and insensitivity to apoptosis possible leading to cancer cell invasion and migration." (PMID 33110136, 2020). "Here, we demonstrate that PTX3 has a ciliogenic effect on different cancer cell types." (PMID 32630309, 2020). "First, PTX3 plays a complicated regulatory role in cancer-related inflammation." (PMID 33219288, 2020). "Furthermore, PTX3 has been described to bind apoptotic and cancer cells and modulate complement activation on these cells through engagement of soluble complement inhibitors." (PMID 33324220, 2020). "PTX3 is a member of the pentraxin family, which is produced locally in response to inflammatory signals and exerts nonredundant functions in various physiopathological conditions, including cancer." (PMID 31480336, 2019). "Biological functions of PTX3 in tissue remodeling and cancer." (PMID 31019517, 2019). "Moreover, we observed a significant increase in the number of PTX3 positive cancer cells in lesions characterized by high value of GG." (PMID 31614564, 2019). "The long pentraxin PTX3 is a prototypic humoral pattern recognition molecule that, in addition to providing defense against infectious agents, plays several functions in tissue repair and regulation of cancer-related inflammation." (PMID 31019517, 2019). "Several lines of evidence indicate that PTX3 could be a local or systemic marker of cancer-related inflammation." (PMID 31019517, 2019). "Here we will review the main biological features of PTX3 focusing on its structure and involvement in sterile conditions of tissue damage and cancer, and providing evidence that microbial and matrix recognition are evolutionarily conserved properties shared by humoral innate immunity molecules." (PMID 31019517, 2019). "In addition, by interacting with a series of ligands and tuning inflammatory responses, PTX3 has various roles in different settings, such as wound healing and tissue remodeling, cardiovascular diseases, fertility, and cancer." (PMID 31031772, 2019). "Recent evidence supports the oncosuppressive role of PTX3 in cancer progression." (PMID 27377307, 2016). "In addition, fibronectin, matrix metalloproteinase-9 (MMP9) and E-cadherin were essential components in EGFR/PTX3-mediated cancer metastasis." (PMID 25797258, 2015). "Long Pentraxin PTX3 is involved in immune escape in cancer cells." (PMID 25797258, 2015). "This study implied that RI37 may be an antagonist of PTX3-enhanced sphere-forming ability, anticancer-drug resistance, migration and invasion of cancer cells." (PMID 26124179, 2015). "However, unlike the well-studied involvement of other pentraxin members in cancer, the biology of PTX3 in cancer is less well understood." (PMID 26124179, 2015). "In this regard, our results show that GBMs and cancer stem cells express PTX3." (PMID 21489226, 2011). "Furthermore, given PTX3’s pivotal role in inflammation and tissue repair, especially in bone remodeling, cancer patients with bone metastases may benefit from PTX3 inhibition, or even TNF-α inhibition, an area that warrants further exploration." (PMID 41479916, 2025). "However, the role of PTX3 in cancer progression is debated and seems context dependent." (PMID 38243273, 2024). "Consequently, PTX3 has been proposed as a potential pan-cancer prognostic marker." (PMID 39594709, 2024). "This may confirm that Pentraxin 3 has a protective and anti-cancer function." (PMID 38136377, 2023). "However, thus far, a systematic pan-cancer analysis of PTX3 remains to be uncharacterized." (PMID 36139597, 2022).
cancer (continued). "In addition, PTX3 had good prediction accuracy of diagnoses across TCGA cancers." (PMID 36139597, 2022). "However, a comprehensive pan-cancer analysis of PTX3 remains to be elucidated." (PMID 36139597, 2022). "In addition, our data showed that PTX3 expression results in activation of Hedgehog signaling and suppression of Hippo signaling, which might shed light on the unsolved question regarding the functional mechanism of PTX3 in cancer regulation." (PMID 32427938, 2020). "Therefore, the multifaceted role of PTX3 in cancer requires further comprehensive study." (PMID 33013829, 2020). "Together, our findings demonstrate for the first time the ability of PTX3 to exert a modulatory effect on primary cilium, shedding a new light on the manifold biological functions of this soluble pattern recognition receptor in embryonic development and cancer." (PMID 32630309, 2020). "Since PTX3 is expressed in inflammatory conditions and acts as a tuner of complement-activation and leukocyte recruitment, it was hypothesized that PTX3 was involved in cancer-related inflammation." (PMID 31019517, 2019). "Therefore, PTX3 may play a vital role at the crossroads of inflammation increase, innate immunity, tissue repair stimulation, and cancer." (PMID 31334115, 2019). "Thus, PTX3 may be a potential target for regulating cancer cell stemness and epithelial-mesenchymal transition, and a plausible therapeutic target or strategy." (PMID 30740360, 2019). "PTX3, similar to CRP, is a key protein in innate immunity, tissue repair, and cancer-related processes." (PMID 41562853, 2025). "For example, pentraxin 3 (PTX3) is a sensitive and specific biomarker with an AUC of 91%, distinguishing PAAD from other cancers." (PMID 40191200, 2025). "PTX3 is elevated in HCC specimens, promoting proliferation, migration, invasion, and EMT phenotype of cancer cells, and independently predicting poor prognosis of HCC patients." (PMID 41479916, 2025). "However, the fact that ATC clearly showed increased concentrations of PTX3 in circulation and higher expression of PTX3 in the tissue samples aligns with previous research indicating that the role of PTX3 in cancer may be context-dependent, influenced by the specific cancer type." (PMID 41373493, 2025). "Following treatment with 5-azacytidine, we found that the PTX3 transcripts were restored in cancer cells but IL-1β and TNF-α exerts a different effect on the induction of PTX3 gene in a cell type-specific manner." (PMID 38243273, 2024). "Ptx3 (pentraxin 3), which increased by 2.6-fold with GEN, is also involved in inflammation and cancer." (PMID 37443838, 2023). "In our previous study, the PTX3 inhibitor RI37 peptides (amino acid 200-236) were developed to prevent the PTX3-induced metastasis and invasion of cancer cells." (PMID 36530573, 2022). "Remarkably, we disclosed that PTX3 was inversely related to ICIs in TGCT, while PTX3 was also negatively correlated with TMB, MSI, and NEO scores in CESC, STAD, and UCEC, indicating the possible resistance to immunotherapy in these cancers." (PMID 36139597, 2022). "Further in depth analysis of human samples confirmed the stromal compartment as the main source of PTX3 and HA, the while TSG-6 appeared to be primarily derived from cancer cells." (PMID 34188166, 2021). "PTX3 organizes hyaluronan in conjunction with tumor necrosis factor-stimulated gene 6 (TSG-6) and facilitates stellate and cancer cell invasion." (PMID 34188166, 2021). "RTKN2, NFIX, PTX3, BMP2 and LOXL2 of the ceRNA network play an important role in cancer progression." (PMID 34394080, 2021). "Pentraxin 3 (PTX3), also known as the TNF-α inducible gene, is an inflammatory molecule involved in the immunological response, inflammation, and cancer." (PMID 34912809, 2021).